RNY1P14 (RNY1 pseudogene 14)
Gene: Miscellaneous RNA gene on chromosome 4 (140,700,835 to 140,700,942, reverse strand). Ensembl gene ENSG00000207155.
Homologues: Orthologues: chimpanzee Y_RNA (98% identical), rat Y_RNA (81% identical), rat Y_RNA (76% identical), rat Y_RNA (75% identical), mouse Gm24203 (74% identical), mouse Gm26456 (74% identical), rat Y_RNA (74% identical), mouse Gm23921 (72% identical), mouse Gm26124 (72% identical), mouse Gm55767 (70% identical), mouse Gm26438 (69% identical), mouse Gm56480 (69% identical), and 3 more. Paralogues in human: RNY1P5 (83% identical), Y_RNA (83% identical), Y_RNA (82% identical), Y_RNA (81% identical), Y_RNA (80% identical), RNY1 (79% identical), RNY1P6 (79% identical), Y_RNA (79% identical), Y_RNA (78% identical), RNY1P1 (77% identical), Y_RNA (77% identical), RNY1P2 (76% identical), and 89 more.